IL6R (interleukin 6 receptor)
Diseases named in the same sentence as IL6R in open-access papers (continued):
Sharing a sentence is not in itself a finding about the gene and the disease.
ovarian carcinoma (36 papers, 2009 to 2025). A malignant neoplasm originating from the surface ovarian epithelium. "In conclusion, our results showed that mRNA levels of IL-6R in ovarian cancer was associated with better prognosis and sensitivity to chemotherapy and can potentially be used as a prognostic marker for this cancer." (PMID 28821817, 2017). "In conclusion, our results showed that mRNA levels of IL-6R in ovarian cancer was positively associated with better prognosis and sensitivity to chemotherapy and can potentially be used as a prognostic marker for this cancer." (PMID 28821817, 2017). "Thus far, EMT in ovarian cancer cells exposed to malignant ascites was linked to the activity of the IL-6/IL-6R axis and signaling through the JAK2-STAT3 pathway." (PMID 30609691, 2019). "In this study, we show that EGF regulates many of the key processes that lead to mesenchymal transition in epithelial ovarian cancer cells and that autocrine signalling through the IL6-R/JAK2/STAT3 pathway is associated with these events and may regulate the metastasis of ovarian carcinoma." (PMID 19088723, 2009). "Recent studies have classified ovarian cancer patients into two categories based on IL6R expression and MDSC cells." (PMID 40427188, 2025). "In ovarian cancer patients, both mAbs have shown good tolerability profiles and effective IL-6/IL-6R blockade, characterised by decreased serum C-reactive protein (CRP) and STAT3 activation and increased serum IL-6 and soluble IL-6R." (PMID 35020853, 2022). "Recent studies found that hsa_circ_0009910 was overexpressed in osteosarcoma and ovarian cancer cells, acting as a sponge of miR-449a and promoting the expression of miR-449a target IL6R in osteosarcoma while suppressing miR-145 in ovarian cancer cells." (PMID 33482819, 2021). "The correlation between SNHG12 and IL-6R in clinical ovarian cancer samples was identified by RT-qPCR." (PMID 32927431, 2020). "Collectively, our data revealed IL-6R as a receptor of IL-6 mediated the regulation of PD-L1 by interrupting the miR-21/IL-6 crosstalk, thus promoting ovarian cancer immune escape." (PMID 32927431, 2020). "To better understand how IL-6R expression is upregulated in ovarian cancer cells, we investigated its transcriptional regulation." (PMID 32927431, 2020). "We analyzed the expression levels of interlukin (IL)-6R and programmed death-ligand 1 (PD-L1) in 51 ovarian cancer and 20 normal specimens by immunohistochemistry." (PMID 32927431, 2020). "Meanwhile, SNHG12 and IL-6R expressions were positively correlated in clinical ovarian cancer samples." (PMID 32927431, 2020). "The present study provides independent evidence that miR-34a regulates the IL-6R/STAT3 pathway in ovarian cancer by demonstrating that IL-6R reexpression is able to mitigate the effects of miR-34a mimetic oligos." (PMID 31448054, 2019). "A previous study showed that IL-6 has the ability to induce apoptosis in many human ovarian cancer developments by blocking the IL-6R/STAT3 pathway." (PMID 31783838, 2019). "Antagonizing IL-6/IL-6R signaling was accepted to have therapeutic activity through inhibition of cytokine network in ovarian cancer cell." (PMID 28821817, 2017). "This study aimed to elucidate potential clinical and biological function of IL-6R mRNA expression in ovarian cancer." (PMID 28821817, 2017). "And this was consistent with Wouters.M’s finding that a high expression of IL-6R protein in ovarian cancer tissue was related to a better DSS19." (PMID 28821817, 2017). "Increased expression of IL-6R protein has been observed in ovarian cancer cell lines, cancer tissue, malignant ascites and serum." (PMID 28821817, 2017). "Despite evidences supported a possible protumor role of IL-6R in ovarian cancer, other studies suggested otherwise." (PMID 28821817, 2017). "In the present study, we firstly analyzed the correlation between the IL-6R mRNA level and its prognostic value in ovarian cancer." (PMID 28821817, 2017).
ovarian carcinoma (continued). "Further prospective studies available of pivotal parameters are needed to verify the prognosis value of IL-6R in ovarian cancer patients." (PMID 28821817, 2017). "IL-6/IL-6R signaling pathway, in particular, has been proposed to be a pivotal cytokine promoting ovarian cancer progression." (PMID 28821817, 2017). "Accumulating evidence suggests a rationale for anti- IL-6/IL-6R therapy for ovarian cancer treatment." (PMID 27825119, 2016). "Four ovarian cancer cell lines including SKOV-3 were tested for expression of IL-6R at mRNA and protein levels." (PMID 27825119, 2016). "Although the IL-6R protein is expressed in all four ovarian cancer cells tested, the expression of IL-6R on plasma membrane but not in cytosol of PA-1 and SKOV-3 cells correlate with ascites induced invasion." (PMID 27825119, 2016). "The data presented herein suggest a rationale for anti-IL-6/IL-6R therapy to suppress the peritoneal spread of ovarian cancer and provide evidence of the therapeutic potential of anti-IL-6R therapy to cure this miserable disease." (PMID 25658637, 2015). "Our study showed that enriched IL-6 secretion from M2-polarized macrophages in ascites promotes ovarian cancer progression through “high” expression of IL-6R in ovarian cancer cells." (PMID 25658637, 2015). "In this study, we first revealed that a high-level of IL-6R expression in cancer tissues is an independent prognosis factor of ovarian cancer patients." (PMID 25658637, 2015). "The ablation of IL-6R function by tocilizumab led to a substantial decrease in tumor progression, suggesting the potential of tocilizumab as a therapeutic strategy for ovarian cancer treatment." (PMID 25658637, 2015). "Against this background, we attempted to analyze the expressional pattern of IL-6R as well as using ovarian cancer TMAs and to evaluate the impact of these expressions on the clinical outcomes of patients." (PMID 25658637, 2015). "The data presented herein suggest a rationale for anti-IL-6/IL-6R therapy to suppress the peritoneal spread of ovarian cancer, and represent evidence of the therapeutic potential of anti-IL-6R therapy for ovarian cancer treatment." (PMID 25658637, 2015). "In conclusion, we showed that “high” IL-6R is an independent prognostic factor of ovarian cancer patients and IL-6 from TAMs present in ascites promotes ovarian cancer invasion, proliferation and angiogenesis." (PMID 25658637, 2015). "Such activation of STAT3 suggests a rationale for a combination of anti-STAT3 and EGFR/IL-6R therapy to suppress the peritoneal spread of ovarian cancer." (PMID 19088723, 2009). "To investigate that, we analysed the activation status of JAK2/STAT3 in ovarian carcinoma specimens and correlated that to STAT3 activation in two ovarian cancer cell lines directly by EGFR or indirectly through IL-6R activation." (PMID 19088723, 2009). "Furthermore, the EGFR/ERK/NFκB and EGFR/PI3K/NFκB pathways play crucial roles in cancer cell proliferation and invasion, which in turn increase IL6 and IL6R expression in chemo-resistant ovarian cancer cells." (PMID 40427188, 2025). "IL-6R and PD-L1 were found to be overexpressed in clinical ovarian cancer specimens." (PMID 32927431, 2020). "And IL-6/IL-6R axis is a potential target for ovarian cancer therapy." (PMID 32190078, 2020). "Our study reveals that SNHG12 facilitates ovarian cancer immune escape by upregulating IL-6R." (PMID 32927431, 2020). "Interestingly, we analyzed clinical biopsy specimens and found that IL-6R and PD-L1 are correlated and highly expressed in ovarian cancer cells." (PMID 32927431, 2020). "Indeed, serum concentrations of the gp130 subunit of the IL-6R were unaffected by siltuximab treatment in patients with ovarian cancer." (PMID 29930760, 2018). "These analyses suggested a possible role of tumoral expression of IL-6R in ovarian cancer." (PMID 28821817, 2017). "IL-6/IL-6R signaling was proved to play a significant role in the progression of ovarian cancer." (PMID 28821817, 2017).
ovarian carcinoma (continued). "As to IL-6R expression, although some have reported that increased IL-6R expression has been observed in ovarian cancer cells, no study has shown the prognostic impact of IL-6R expression in ovarian cancer tissues on patients." (PMID 25658637, 2015). "There is increasing evidence that IL-6/IL-6R signaling may play a significant role in the progression of various cancers, including ovarian carcinomas." (PMID 25658637, 2015). "Therefore, we were encouraged to investigate the clinical values of IL-6 and IL-6R in ovarian cancer tissues using the tissue microarrays (TMAs) we constructed and the corresponding clinical data." (PMID 25658637, 2015). "It appears that antagonizing IL-6/IL-6R signaling may have therapeutic activity in patients with ovarian cancer through the inhibition of a tumor-promoting cytokine network." (PMID 25658637, 2015). "Of 94 patients, 32 (34.0%) showed “high” IL-6R expression, including 14 of 34 serous (41.1%), 3 of 16 mucinous (18.8%), 1 of 11 endometrioid (9.1%), 10 of 20 clear cell (50.0%) and 4 of 13 other (30.8%) ovarian carcinomas." (PMID 25658637, 2015). "Since IL-6/IL-6R signaling contributed to ovarian cancerprogression in a paracrine way, we considered that inflammatory microenvironments surrounding ovarian cancers may constitute cytokine-rich environments, especially by producing IL-6." (PMID 25658637, 2015). "The pretreatment of anti-IL-6R antibody inhibited those reactions in a dose-dependent manner, indicating that IL-6R is highly expressed in certain types of ovarian cancer cells and that IL-6/IL-6R signaling exerts in a paracrine manner in these cells, even though the cells do not produce IL-6." (PMID 25658637, 2015). "In order to determine whether ovarian cancer cell lines predominantly express the full-length (IL-6R) or the differentially spliced isoform that lacks the transmembrane domain (sIL-6R), we designed primers that code splicing lesions and performed RT-PCR." (PMID 25658637, 2015). "EGFR and IL-6R signaling cross-talk through JAK2/STAT3 to mediate EMT in ovarian carcinomas; activated STAT3 in high-grade ovarian carcinomas may occur directly through activation of EGFR/IL-6R or indirectly through induction of IL-6R signaling." (PMID 25566498, 2014). "To determine if mRNA increase in IL-6R expression in response to EGF treatment has any affect on the production of IL-6 in ovarian cancer cell lines, we used IL-6 sandwich ELISA to quantify the amount of IL-6 secreted by OVCA 433 and SKOV3 cell lines in response to EGF." (PMID 19088723, 2009). "We studied the association between the increased levels of STAT3 activation and high-grade ovarian carcinomas, consistent with a role for STAT3 in the motile phenotype of ovarian cancer cells in response to direct activation by EGFR or indirectly through IL-6R." (PMID 19088723, 2009). "Both OVCA 433 and SKOV3 cell lines produced IL-6 endogenously but, in the presence of EGF, the production of IL-6 was increased (P<0.05) in the serum-free medium of both ovarian cancer cell lines, consistent with the mRNA enhancement of IL-6 and IL-6Rα on the cells." (PMID 19088723, 2009). "We detected IL-6R expression in clinical ovarian cancer patient’s sample by IHC and found that IL-6R expression was much higher in ovarian cancer tissues (p < 0.05), which might indicate that high levels of IL-6R would be required for PD-L1 induced via the miR-21/IL-6 feedback loop." (PMID 32927431, 2020). "Thus, IL-6/IL-6R mediated JAK2-STAT3 signaling pathway could be a promising therapeutic target for anticancer therapy in ovarian cancer patients with ascites." (PMID 27825119, 2016). "In light of various publications highlighting the importance of IL-6/IL-6R signaling in ovarian tumor biology and the results described here, we are supportive of clinical trials to study whether antagonizing IL-6R is a viable treatment strategy for ovarian cancer." (PMID 25658637, 2015).
ovarian carcinoma (continued). "Hence, diminution in EGFR/IL-6R/STAT3 signalling may represent novel therapeutic targets for pharmacological intervention in the management of ovarian cancer progression." (PMID 19088723, 2009). "We observed that MAP1LC3B was inversely correlated with IL6R and SLC2A1 mRNA expression in ovarian cancer patients TCGA data set." (PMID 36675246, 2023). "Ovarian cancer cells secrete IL6 and IL6Rα (soluble form sIL-6R) through trans-signaling sIL6R-IL6 in the pro-inflammatory microenvironment cells that do not express transmembrane receptor to facilitate angiogenesis via increasing the VEGF expressions." (PMID 37792745, 2023). "A second phase I/II trial in ovarian cancer investigated the combination of the ICD inducing chemotherapeutics carboplatin or doxorubicin in combination with tocilizumab, an anti-IL-6R antibody, and pegylated IFN-⍺ (NCT01637532)." (PMID 34497771, 2021). "In order to assess the therapeutic potential of IL-6R, we established TMA slides from 94 Japanese ovarian cancer patient." (PMID 25658637, 2015). "Notably, we found that OSMR, LIFR, IL6R, and IL6ST mRNA were highly upregulated in cisplatin-resistant ovarian cancer cells in both A2780 and OVCAR8 cells." (PMID 38839865, 2024). "Currently, the application of IL-6/IL-6Rα/gp130 blockers as anti-cancer agents has not been extensively studied, much less for ovarian cancer." (PMID 37047012, 2023). "We previously reported that downregulation of the IL-6R/STAT3 signaling pathway did not affect total STAT3 expression in three ovarian cancer cell lines, as consistent with this study." (PMID 31448054, 2019). "Moreover, structurally-related members of the IL-6R family, including IL-6R and G-CSFR, have been shown to contribute to ovarian cancer progression." (PMID 29212170, 2017). "Importantly, aberrant signaling by IL-6R and G-CSFR has been shown to contribute to key ovarian cancer phenotypes, including proliferation, migration and resistance against apoptosis." (PMID 29212170, 2017). "Targeting IL-6, IL-6R or JAK2/STAT3 may offer an efficient management of ascites induced migration and invasion in ovarian cancer patients." (PMID 27825119, 2016). "Exogenous treatment of IL-6 also significantly enhanced the proliferation of both ovarian cancer cells in a dose dependent manner (IL-6 100ng/ml; SKOV3ip1, 1.60 ± 0.29 fold, RMG-1, 1.64 ± 0.39 fold) and the pretreatment of anti-IL-6R antibody almost abolished these enhancements." (PMID 25658637, 2015). "Collectively, exogenous treatment with IL-6 induced proliferation, invasion and VEGF production of ovarian cancer cells, even though they do not express IL-6, and co-treatment with soluble IL-6R was not required." (PMID 25658637, 2015). "The addition of exogenous sIL-6R did not further promote the invasion of ovarian cancer cells induced by IL-6, suggesting that IL-6Rs (IL-6R and sIL-6R) produced from cancer cells are enough to activate IL-6/IL-6R signaling." (PMID 25658637, 2015). "Since “high” expression of IL-6R but not IL-6 affected the prognoses of patients with ovarian cancer, we quantified the expressions of IL-6 and IL-6R in ovarian cancer cell lines by real-time RT-PCR." (PMID 25658637, 2015). "The targeting of multiple signaling pathways such as VEGFR, EGFR, IL-6R-JAK-STAT3/NF-κB, PI3K/AKT/mTOR, and ABC drug transporters in ovarian cancer may be an auspicious start to favourable PFS and OS outcomes." (PMID 22481932, 2012). "From that perspective, IL-6R and GP130 family of receptors may form an extensive network of P-STAT3 signalling systems in ovarian carcinomas." (PMID 19088723, 2009). "Early‐phase clinical trials have assessed the efficacy of IL6R‐blocking antibodies in EOC patients, pioneered by the assessment of tocilizumab combined with interferon‐alpha or siltuximab in patients with chemoresistant ovarian cancer, showing promising response rates." (PMID 39245677, 2025).
ovarian carcinoma (continued). "Moreover, we show that IL-6, but not IL-8, is one of the major cytokines in CAF-CM that contributes to HK2 up-regulation through binding of IL-6R in ovarian cancer cells, suggesting that HK2 expression can be regulated by the tumor microenvironment in ovarian cancer." (PMID 31212816, 2019). "Since IL-6/IL-6R signaling is known to act in a number of ways to augment cancer progression, we examined whether the exogenous treatment of IL-6 enhances proliferation, invasion and VEGF-related angiogenesis in ovarian cancer cells." (PMID 25658637, 2015). "Exogenous treatment of IL-6 robustly induced cell invasion of ovarian cancer cells in a dose dependent manner (IL-6 100ng/ml; SKOV3ip1, 4.27 ± 0.53 fold, RMG-1, 2.99 ± 0.46 fold), whereas the induction was almost completely inhibited by the pretreatment with anti-IL-6R antibody." (PMID 25658637, 2015). "Consistent with this fact, neutralising anti-IL6R partially inhibited EGF-induced migration in OVCA 433 cells, suggesting that EGF-induced migratory phenotype is dependent to a certain extent on the EGF-induced expression of IL-6 in certain ovarian cancer cells." (PMID 19088723, 2009). "Among patients with ovarian cancer, those who had “high” IL-6R expression showed significantly worse PFS than those who had “low” or negative IL-6R expression (PFS, 23.8 vs. 32.3 months, P = 0.0029)." (PMID 25658637, 2015).